ZNF622 (zinc finger protein 622)
Description:
Pre-60S-associated cytoplasmic factor involved in the cytoplasmic maturation of the 60S subunit.
Synonyms: ZPR9; MGC2485; MGC17552
Tractability: Small molecule: a structure with a bound ligand is known. PROTAC: UniProt records ubiquitination sites on it; ubiquitination databases record sites on it; its protein half-life has been measured.
Gene: Protein-coding gene on chromosome 5 (16,451,518 to 16,465,811, reverse strand). Ensembl gene ENSG00000173545.
Subcellular location: Cytoplasm; Nucleus
Subcellular location (Human Protein Atlas): Cytosol; Golgi apparatus; Nucleoli; Nucleoplasm
Gene Ontology:
Molecular function: preribosome binding; protein binding; RNA binding; nucleic acid binding; zinc ion binding
Biological process: intrinsic apoptotic signaling pathway in response to oxidative stress; positive regulation of apoptotic process; positive regulation of JNK cascade; positive regulation of kinase activity; positive regulation of MAPK cascade; ribosomal large subunit biogenesis
Cellular component: cytosol; nucleolus; nucleoplasm; preribosome, large subunit precursor; cytoplasm; nucleus
Genetic constraint (gnomAD): Loss-of-function variants: 31 observed, 46.1 expected, observed/expected ratio (o/e) 0.67, 90% interval 0.5 to 0.91. The upper end of that interval is the gene's LOEUF score, 0.91, which puts it in group 3 of 6, group 1 being the genes least tolerant of losing a copy. Missense variants: 554 observed, 610.85 expected, observed/expected ratio (o/e) 0.91, 90% interval 0.85 to 0.97. Synonymous variants: 203 observed, 228.3 expected, observed/expected ratio (o/e) 0.89, 90% interval 0.79 to 1.
Homologues: Orthologues: chimpanzee ZNF622 (99% identical), macaque ZNF622 (97% identical), rabbit ZNF622 (91% identical), guinea pig ZNF622 (88% identical), pig ZNF622 (83% identical), mouse Zfp622 (82% identical), dog ZNF622 (79% identical), rat Zfp622l1 (78% identical), tropical clawed frog znf622 (69% identical), zebrafish znf622 (61% identical), Drosophila melanogaster CG6769 (40% identical), Caenorhabditis elegans znf-622 (32% identical).
Diseases named in the same sentence as ZNF622 in open-access papers:
ZNF622 is named in the same sentence as 8 diseases in open-access papers, as found by Europe PMC text mining. Sharing a sentence is not in itself a finding about the gene and the disease. The quoted sentences say what the papers report.
Hepatic steatosis (2 papers, 2020 to 2022). Steatosis is a term used to denote lipid accumulation within hepatocytes. "In contrast, a region (Chr2: 75160695-75163487) with increased hyper-acetylation in FLHS was identified near ZNF622, consistent with the known role of this gene in hepatic steatosis." (PMID 33505421, 2020). "Additionally, peripheral blood leukocyte ACSL4, CRLS1, CTP1A, SIGIRR, SSBP1, and ZNF622 genes containing DMPs might be used as serum biomarkers to stratify NAFLD patients into groups with simple hepatic steatosis and NASH." (PMID 35433752, 2022).
adenovirus infection (1 paper, 2021). "Although an association between ZNF622 and cancer has not been reported yet, its role as an antiviral protein upon adenovirus infection was proposed." (PMID 34298834, 2021).
neuroblastoma (1 paper, 2021). Neuroblastoma (NB) is the most common solid, extracranial childhood tumor. "ZNF622 (zinc finger protein 622), also known as ZPR9 (zinc finger protein 9), enhances the transcriptional activity of the MYBL2 (also known as B-MYB) transcription factor to regulate cellular growth of neuroblastoma cells, but may also have cytoplasmic roles in the regulation of apoptosis." (PMID 34283051, 2021).
prostate carcinoma (1 paper, 2021). A carcinoma that arises from epithelial cells of the prostate gland. "A literature review focusing on AR, GATA3 and ZNF622 regulation of glycogenes identified a single paper reporting AR binding to a B3GNT5 promoter, using semi-quantitative PCR with ChIP in prostate cancer cell line LAPC-4." (PMID 34283051, 2021).
ZNF622 also shares sentences with these, for which no sentence is quoted: cancer (2 papers); mental disorder (1); Obesity (1); viral infection (1).